GRID2 (glutamate ionotropic receptor delta type subunit 2)
Description:
Member of the ionotropic glutamate receptor family, which plays a crucial role in synaptic organization and signal transduction in the central nervous system. Although it shares structural features with ionotropic glutamate receptors, does not bind glutamate as a primary ligand. Promotes synaptogenesis and mediates the D-serine-dependent long term depression signals and AMPA receptor endocytosis of cerebellar parallel fiber-Purkinje cell (PF-PC) synapses through the NRX1B-CBLN1-GRID2 triad complex. In the presence of neurexins and cerebellins, forms cation-selective channels that are proposed to be gated by glycine and D-serine. Cation-selective ion channel activity can be triggered by GRM1 in Purkinje cells.
Synonyms: GluD2; GluR-delta-2; SCAR18
Tractability: Small molecule: it belongs to a druggable protein family. Antibody: its Gene Ontology location is reachable by antibodies, with high confidence; UniProt places it where antibodies can reach, with medium confidence; UniProt predicts a signal peptide or a membrane-spanning region.
Gene: Protein-coding gene on chromosome 4 (92,303,966 to 93,810,157, forward strand). Ensembl gene ENSG00000152208.
Subcellular location: Postsynaptic cell membrane
Gene Ontology:
Molecular function: protein binding; transmitter-gated monoatomic ion channel activity involved in regulation of postsynaptic membrane potential; AMPA glutamate receptor activity; glutamate receptor activity; PDZ domain binding; scaffold protein binding; identical protein binding; ligand-gated monoatomic ion channel activity; monoatomic ion channel activity; signaling receptor activity
Biological process: excitatory synapse assembly; positive regulation of long-term synaptic depression; positive regulation of synapse assembly; synaptic signaling via neuropeptide; cerebellar granule cell differentiation; excitatory postsynaptic potential; glutamate receptor signaling pathway; heterophilic cell-cell adhesion; intracellular protein localization; modulation of chemical synaptic transmission; prepulse inhibition; regulation of neuron apoptotic process; synaptic transmission, glutamatergic; ionotropic glutamate receptor signaling pathway; monoatomic ion transmembrane transport; monoatomic ion transport; regulation of postsynaptic density assembly; regulation of postsynaptic membrane neurotransmitter receptor levels; regulation of postsynaptic membrane potential; regulation of presynapse assembly; regulation of synapse assembly; regulation of synaptic plasticity; signal transduction; trans-synaptic signaling by trans-synaptic complex, modulating synaptic transmission
Cellular component: postsynaptic density membrane; AMPA glutamate receptor complex; dendritic spine; ionotropic glutamate receptor complex; plasma membrane; postsynaptic membrane; synapse; glutamatergic synapse; membrane; parallel fiber to Purkinje cell synapse; somatodendritic compartment
Genetic constraint (gnomAD): Loss-of-function variants: 7 observed, 39.6 expected, observed/expected ratio (o/e) 0.18, 90% interval 0.1 to 0.33. The upper end of that interval is the gene's LOEUF score, 0.33, which puts it in group 1 of 6, group 1 being the genes least tolerant of losing a copy. Missense variants: 528 observed, 602.98 expected, observed/expected ratio (o/e) 0.88, 90% interval 0.81 to 0.94. Synonymous variants: 228 observed, 231.96 expected, observed/expected ratio (o/e) 0.98, 90% interval 0.88 to 1.1.
Homologues: Orthologues: chimpanzee GRID2 (99% identical), macaque GRID2 (99% identical), dog GRID2 (99% identical), pig GRID2 (99% identical), guinea pig GRID2 (98% identical), rabbit GRID2 (98% identical), rat Grid2 (98% identical), mouse Grid2 (98% identical), tropical clawed frog grid2 (89% identical), zebrafish grid2 (82% identical), Drosophila melanogaster clumsy (22% identical), Drosophila melanogaster Grik (20% identical), and 30 more. Paralogues in human: GRID1 (56% identical), GRIK1 (25% identical), GRIK2 (25% identical), GRIK3 (25% identical), GRIA2 (24% identical), GRIA4 (24% identical), GRIA3 (24% identical), GRIK4 (23% identical), GRIA1 (23% identical), GRIK5 (23% identical), GRIN1 (21% identical), GRIN2C (19% identical), and 5 more.
Diseases named in the same sentence as GRID2 in open-access papers:
GRID2 is named in the same sentence as 58 diseases in open-access papers, as found by Europe PMC text mining. Sharing a sentence is not in itself a finding about the gene and the disease. The quoted sentences say what the papers report.
Ataxia (21 papers, 2009 to 2024). Ataxia refers to impaired coordination of voluntary muscle movement. "Research has shown that a higher proportion of patients with early-onset cerebellar atrophy and ataxia carry variants in SNX14 (9.88%) compared to other known pathogenic genes such as GRID2 (2.47%), NPC1 (1.23%), and SETX (1.23%)." (PMID 38655056, 2024). "By contrast, GRID2 variants demonstrated more consistent phenotypic characteristics including spinocerebellar ataxia and oculomotor symptoms, suggestive of pathogenicity, but further functional studies as well as genetic trio studies are needed." (PMID 37944084, 2024). "Loss-of-function variation in GRID2 has been implicated in an autosomal recessive syndrome with cerebellar ataxia, eye movement abnormalities, cerebellar atrophy, and global developmental delay." (PMID 37944084, 2024). "We also analyzed the co-expression network of those ataxia risk genes and revealed a central role of Eef2, Grid2, Tubb4a in the co-expression networks, while Ttbk2 and Bean1 have few interactions with other ataxia risk genes." (PMID 30690467, 2019). "Mutations in the GRID2 gene encoding for GluD2 have been recently associated with cerebellar ataxia in several patients." (PMID 29760657, 2018). "Monoallelic or biallelic GRID2 mutations were recently reported in rare cases with cerebellar syndrome and variable degree of ataxia, ocular symptoms, hypotonia and developmental delay." (PMID 29207948, 2017). "The combined clinical, radiological and genetic findings add further genotype-phenotype correlations to GRID2 associated ataxia." (PMID 29207948, 2017). "In 2013, two families were identified in which a homozygous deletion of GRID2 exon 4 and compound heterozygous deletions involving GRID2 exon 2, respectively, were associated with cerebellar ataxia, tonic upgaze and delayed cognitive and speech development." (PMID 26377184, 2015). "Recently, a de novo 276-kb deletion encompassing the first exon of the GRID2 gene encoding GluRδ2 was reported in a single patient, associated with cerebellar ataxia but also spastic paraplegia, frontotemporal dementia and lower motor neuron disease." (PMID 26377184, 2015). "Recently, the first mutations in the human GRID2 gene have been reported in patients with cerebellar ataxia." (PMID 24797279, 2014). "Both loss-of-function and gain-of-function mutations in the Grid2 gene encoding GluD2 result in defects in Purkinje cell dendritic arborization and cerebellar ataxia." (PMID 24797279, 2014). "Homozygous and compound heterozygous partial deletions of the GRID2 gene (exons 4 and 2) have been identified to cause nystagmus, hypotonia with developmental delay in gross motor skills, encephalopathy with cerebellar ataxia, oculomotor apraxia, and pyramidal tract involvement." (PMID 36671517, 2023). "In addition, single nucleotide variants in the GRID2 gene have been reported to cause congenital to mild adult-onset cerebellar ataxia." (PMID 36671517, 2023). "Therefore, we should also screen for the GRID2 mutation in ADCA families with pure cerebellar ataxia." (PMID 35882834, 2022). "We should screen for GRID2 variants in the case of families with pure cerebellar ataxia in ADCA." (PMID 35882834, 2022). "The link between GluD2 and ataxia is strongly supported by several studies in mice with different mutations in the Grid2 gene, that have provided important information about the role of the GluD2 receptor in cerebellar functions and how their mutations affect cerebellar circuitry and cause ataxia." (PMID 29760657, 2018). "Furthermore, heterozygous GRID2 mutations, including three missense variants, have been identified in rare cases with variable onset of cerebellar ataxia, ocular symptoms and cognitive impairment." (PMID 29207948, 2017).
Ataxia (continued). "GRID2 is the receptor for excitatory glutamate neurotransmitter in the cerebellum and homozygous deletions, ranging from 37 kb–335 kb in size, were reported to cause cerebellar ataxia and atrophy (MIM#616204)." (PMID 27435318, 2016). "Finally, mutations in the Grid2 gene have been found to be the cause of ataxia in ‘lurcher’ mice, which are characterised by apoptosis of PCs during postnatal development, and ‘hotfoot’ mice." (PMID 26377184, 2015). "Similarly, it took 59 years after the initial discovery of the Lurcher mutant, until the identification of the first human mutations in GRID2 in patients with cerebellar ataxia." (PMID 24797279, 2014). "Transgenic mice with Grid2 knockout (the hotfoot strain) exhibit ataxia, impaired locomotion, and Purkinje cell abnormalities, and implicate GluD2 receptor involvement in cerebellar synaptic long term depression, as well as cerebellar synaptic organization." (PMID 37944084, 2024). "Downregulated transcripts were found for the ATM interactome component Usp2, many non-coding RNAs, ataxia genes Itpr1, Grid2, immediate early genes and immunity factors." (PMID 37830614, 2023). "Approximately 3 weeks after birth, CTCF-cKO mice, represented by the genotype Ctcf;Grid2-Cre (fl/fl; +/Cre), showed obvious differences in appearance with growth retardation and ataxia-like motor abnormalities as compared with mice of other genotypes." (PMID 36447271, 2022). "Further studies are required to elucidate the genotype-phenotype correlation in GRID2-related ataxias." (PMID 35882834, 2022). "Disruptions in the GRID2 gene were described in several family cases with cerebellar ataxia and in a mouse model." (PMID 35159210, 2022). "We find that splicing aberrations disrupt the expression of many key cerebellar PC genes, many of which (e.g., Itpr1, Grid2, Ca8, Bean1, etc.)can individually compromise cerebellar function and lead to ataxia." (PMID 34910524, 2021). "We have previously demonstrated, in a different rodent model of cerebellar ataxia, that the expressions of Calb1, Pcp2 and Grid2, as well as that of some other genes highly expressed in PCs, significantly reduce as the disease phenotype progresses." (PMID 27013529, 2016). "Mice with an impaired Grid2 gene exhibit a broad range of phenotypes, such as cerebellar ataxia, poor motor learning, and memory dysfunction." (PMID 25513882, 2014). "Unlike GRID1 where phenotypes were variable, GRID2 missense and nonsense variants presented with ataxia (n = 20) and cerebellar atrophy (n = 6), consistent with the phenotypic characteristics of mutant Grid2 lurcher mice." (PMID 37944084, 2024). "Thus, in the double-mutant cerebellum, widespread abnormalities occur, involving a notable cohort of critical neuroregulatory genes including Itpr1, Grid2, and Ca8, whose perturbation in humans underpin ataxia syndromes." (PMID 34910524, 2021). "Here, we report a new deletion in the mouse Grid2 gene that is accompanied by ataxia." (PMID 25513882, 2014). "This phenomenon can be exemplified by recent reports of glutamate receptor, ionotropic, delta 2 (GRID2, MIM 616204), which can contribute to neurodevelopmental disorders and ataxia through recessive and de novo SNVs as well as homozygous and de novo partial CNV deletions." (PMID 28327206, 2017).
schizophrenia (8 papers, 2009 to 2024). A major psychotic disorder characterized by abnormalities in the perception or expression of reality. "In addition, a deletion affecting the GRID2 gene has been associated with schizophrenia." (PMID 37944084, 2024). "To understand the variation that may disrupt gene function, we identified known missense, nonsense, and deletion variants in GRID1 and GRID2 from the public database ClinVar, the Schizophrenia Exome Sequencing Meta-analysis (SCHEMA) database, and published reports in the literature." (PMID 37944084, 2024). "Rs2133450 is in the glutamate metabotropic receptor GRM7 and rs1875705 in the NMDA receptor subunit GRID2, likely modulating glutamatergic neurotransmission, whose dysfunction contributes to schizophrenia." (PMID 38523642, 2024). "Others participate in neurodegenerative conditions; PD, schizophrenia, and intellectual disability (Tenm4, Pde4dip, Grid2, Arhgap18)." (PMID 36902345, 2023). "We tested candidate genes on a cohort of schizophrenia-associated hiPSC-derived neurons and found blunted expression profiles for COX7A2, GRID2 and HOMER1 using quantitative PCR." (PMID 29691375, 2018). "Presently, no other pharmacogenomic studies have examined GRID2 in the context of antipsychotic treatment for early episode psychosis or schizophrenia." (PMID 26905411, 2016).
autism (5 papers, 2016 to 2022). Persistent deficits in social interaction and communication and interaction as well as a markedly restricted repertoire of activity and interest as well as repetitive patterns of behavior. "Hub genes of the turquoise module included one GABA receptor encoding genes such as Gabrb1, one glutamate receptor gene (Grid2) and genes tightly associated with synaptic development and autism (Nrxn1, Lrfn5, Plcb1, Erc2, Frmpd4, Tanc2, Ctnnd2, Dmd)." (PMID 34021132, 2021). "Except for ARC, GRIK2 and GRID2, belonging to inotropic glutamatergic receptors, were shown to participate in neurodegeneration and psychiatric diseases, such as autism, Huntington disease and major depression." (PMID 33969375, 2021).
depression (4 papers, 2020 to 2023). "The GRID2 gene is highly expressed in brain and associated with depression." (PMID 33232274, 2020). "Genes associated with depression or neuro-diseases were found in this study, such as ABCG1, ASMTL, CACNA1F, COX7A1, GRID2, HTR3E, and SHANK2." (PMID 37766304, 2023). "In the restrained group, genes involved in long-term depression (Plcb4, Gucy1a3, Prkg2, Ppp1r17, Grid2, and Crhr1) were downregulated compared to the control group." (PMID 34276303, 2021).
gastric cancer (4 papers, 2020 to 2023). A primary or metastatic malignant neoplasm involving the stomach. "Base on previous studies, GRID2 may be a biological marker for the prognosis of gastric cancer, and upregulated GRID2 is an independent risk factor for gastric cancer." (PMID 37964339, 2023). "Previous studies have shown that Grid2 is closely related to the occurrence and prognosis of gastric cancer and many other diseases." (PMID 37964339, 2023). "Previous study has confirmed that GRID2 was related to the inferior survival outcome of prostate and gastric cancers." (PMID 34335109, 2021). "The risk score was constructed based on 4 genes (GRID2, ATG4D,GABARAPL2, CXCR4), and gastric cancer patients were significantly divided into high-risk and low-risk groups according to overall survival." (PMID 32477008, 2020). "Notably, BIRC5 has been explored as one of the hub ATGs in the prognostic signatures of breast cancer, prostate cancer, and human endometrial cancer, as well as GRID2 in gastric cancer and endometrial carcinoma." (PMID 34746127, 2021).
Anxiety (2 papers, 2021 to 2023). Intense feelings of nervousness, tension, or panic often arise in response to interpersonal stresses. "Multiple high-confidence ASD risk genes associated with anxiety were dysregulated in our RNA-seq data including TMLHE and GRID2, DNAH10, GRIA1, SLC6A4, and IGF1." (PMID 37486945, 2023). "Ppp1r17 and Grid2 have not been studied in the context of anxiety." (PMID 34276303, 2021).
autosomal dominant cerebellar ataxia (2 papers, 2022 to 2025). A clinically and genetically heterogeneous group of neurodegenerative diseases characterized by a slowly progressive ataxia of gait, stance and limbs, dysarthria and/or oculomotor disorder, due to cerebellar degeneration in the absence of coexisting diseases. "A heterozygous mutation in GRID2 that causes SCAR18 was first reported in an Algerian family with autosomal dominant cerebellar ataxia (ADCA)." (PMID 35882834, 2022).
epilepsy (2 papers, 2017). A brain disorder characterized by episodes of abnormally increased neuronal discharge resulting in transient episodes of sensory or motor neurological dysfunction, or psychic dysfunction. "Among the list of mRNAs predicted targets anticorrelated with significantly differentially expressed miRNAs in the chronic stage of epilepsy, of note is the glutamate ionotropic receptor δ type 2 (Grid2), which is anticorrelated with miR-130a-3p, miR-148b-3p, and miR-551b-3p." (PMID 29291240, 2017).
Obesity (2 papers, 2021 to 2025). Accumulation of substantial excess body fat. "GRID2 (glutamate receptor, ionotropic, delta 2) is selectively expressed in Purkinje cells in the cerebellum, and at first glance is weakly associated with obesity." (PMID 33805313, 2021).
Alzheimer disease (1 paper, 2023). A progressive, neurodegenerative disease characterized by loss of function and death of nerve cells in several areas of the brain leading to loss of cognitive function such as memory and language. "CSC and CB microglia also express more GRID2, previously detected in brain microglia of Alzheimer’s disease donors, and more HIF1A and NEAT1, which may indicate a hypoxic stress response." (PMID 37217978, 2023).
anaphylaxis (1 paper, 2019). An acute hypersensitivity reaction that occurs from exposure to an allergen. "This approach identified several genes that are associated with aging (ATP2B2, CAV3, CNTN3, CTNNA2, GRID2), inflammation (ATP2B2, CAV3, RAD18, KBTBD8), vascular permeability (SFXN5, RAD18) and anaphylaxis (CAV3, RAD18, CTNNA2, ATP2B2 and GRID2)." (PMID 31701027, 2019).
childhood absence epilepsy (1 paper, 2010). A familial generalized pediatric epilepsy, characterized by very frequent (multiple per day) absence seizures, usually occurring in children between the ages of 4 and 10 years, with, in most cases, a good prognosis. "Case ND05260 (childhood absence epilepsy, CAE) carries a 647-kb deletion within the GRID2 gene, which encodes a glutamate receptor expressed in the cerebellum, and a 1-Mb duplication of 9q31." (PMID 20502679, 2010).
COVID-19 (1 paper, 2023). A disease caused by infection with severe acute respiratory syndrome coronavirus 2. "This study identified SVs impacting genes implicated in neurological functions in patients with neurological manifestations of COVID-19, of which, two SVs in PRKN and GRID2 genes are the most interesting candidates." (PMID 36671517, 2023).
deafness (1 paper, 2023). An inherited or acquired condition characterized by the complete loss of the ability to hear from one or both ears. "Defects in the 30 shared genes are related to several pathologies, such as vision abnormalities (TMEM135), cancer (CDH6, FZD10, TIAM2), neuropsychiatric disorders (Tenm4, Pde4dip, Grid2), deafness (TFB1M), neutrophil disorders (VPS45) and others." (PMID 36902345, 2023).
Encephalopathy (1 paper, 2023). Encephalopathy is a term that means brain disease, damage, or malfunction. "Similarly, in the case of the 71-year-old male with the partial deletion of the GRID2 gene, the incidental SARS-CoV-2 infection concomitantly resulted in the development of encephalopathy." (PMID 36671517, 2023).
glioma (1 paper, 2021). A benign or malignant brain and spinal cord tumor that arises from glial cells (astrocytes, oligodendrocytes, ependymal cells). "From the Human Protein Atlas database, immunohistochemistry results showed that GRID2 and GRIK2 were up-regulated in gliomas than normal brain tissue." (PMID 33969375, 2021).